XYLT2 (xylosyltransferase 2)
Description:
Catalyzes the first step in the biosynthesis of chondroitin sulfate, heparan sulfate and dermatan sulfate proteoglycans, such as DCN. Transfers D-xylose from UDP-D-xylose to specific serine residues of the core protein.
Synonyms: XT-II; XylT-II; XT2; PXYLT2; SOS
Tractability: Antibody: UniProt places it where antibodies can reach, with high confidence; UniProt predicts a signal peptide or a membrane-spanning region; its Gene Ontology location is reachable by antibodies, with medium confidence. PROTAC: ubiquitination databases record sites on it; its protein half-life has been measured.
Safety:
Unwanted effects reported when the protein is acted on. In parentheses: how it was acted on, where the effect was seen, and who reports it.
thrombocytopenia (source: ClinPGx)
Gene: Protein-coding gene on chromosome 17 (50,346,080 to 50,363,138, forward strand). Ensembl gene ENSG00000015532.
Subcellular location: Golgi apparatus membrane; Secreted
Pathways (Reactome):
Metabolism: Glycosaminoglycan-protein linkage region biosynthesis
Gene Ontology:
Molecular function: magnesium ion binding; manganese ion binding; protein xylosyltransferase activity; glycosyltransferase activity; UDP-glycosyltransferase activity
Biological process: chondroitin sulfate proteoglycan biosynthetic process; heparan sulfate proteoglycan biosynthetic process; glycosaminoglycan biosynthetic process; glycosaminoglycan-protein linkage region biosynthetic process; proteoglycan biosynthetic process
Cellular component: extracellular region; Golgi apparatus; Golgi membrane; membrane
Genetic constraint (gnomAD): Loss-of-function variants: 37 observed, 70.69 expected, observed/expected ratio (o/e) 0.52, 90% interval 0.4 to 0.69. The upper end of that interval is the gene's LOEUF score, 0.69, which puts it in group 2 of 6, group 1 being the genes least tolerant of losing a copy. Missense variants: 895 observed, 1,081.2 expected, observed/expected ratio (o/e) 0.83, 90% interval 0.78 to 0.88. Synonymous variants: 459 observed, 454.89 expected, observed/expected ratio (o/e) 1.01, 90% interval 0.93 to 1.09.
Homologues: Orthologues: chimpanzee XYLT2 (99% identical), dog XYLT2 (95% identical), rabbit XYLT2 (94% identical), pig XYLT2 (94% identical), mouse Xylt2 (94% identical), rat Xylt2 (94% identical), guinea pig XYLT2 (89% identical), tropical clawed frog xylt2 (67% identical), zebrafish xylt2 (61% identical), Drosophila melanogaster oxt (35% identical), Caenorhabditis elegans sqv-6 (25% identical), Caenorhabditis elegans F26D2.3 (8% identical), and 16 more. Paralogues in human: XYLT1 (55% identical), WSCD1 (12% identical), WSCD2 (11% identical), GCNT1 (11% identical), GCNT3 (11% identical), GCNT4 (11% identical), GCNT2 (10% identical), GCNT7 (8% identical).
Diseases named in the same sentence as XYLT2 in open-access papers:
XYLT2 is named in the same sentence as 30 diseases in open-access papers, as found by Europe PMC text mining. Sharing a sentence is not in itself a finding about the gene and the disease. The quoted sentences say what the papers report.
spondylo-ocular syndrome (7 papers, 2019 to 2025). Spondylo-ocular syndrome is a very rare association of spinal and ocular manifestations that is characterized by dense cataracts, and retinal detachment along with generalized osteoporosis and platyspondyly. "Mutations in XYLT2 are also associated with a disease phenotype known as spondylo-ocular syndrome, which is characterized by short stature, retinal detachment, amblyopia, nystagmus, heart valve defects, bone fragility, and mild learning difficulties." (PMID 39941041, 2025). "Spondyloocular syndrome (SOS) [OMIM:605822] is a rare AR CDG caused by mutations in the XYLT2 gene located on chromosome 17q21.33." (PMID 37239976, 2023). "For example, deficiencies in XYLT1 and XYLT2, both which encode xylosyl transferases and are involved in the linker synthesis, cause Desbuquois dysplasia type 2 and spondyloocular syndrome, respectively." (PMID 36233030, 2022). "Biallelic variants in XYLT1 and XYLT2, encoding xylosyltransferases, are associated with Desbuquois dysplasia type 2 and spondylo-ocular syndrome, respectively." (PMID 31438591, 2019). "Molecular defects in XYLT1 have been associated with Desbuquois dysplasia type 2 (DBQD2) with 28 molecularly proven patients reported hitherto, while XYLT2 mutations cause the so-called spondylo-ocular syndrome (SOS), which has been described in 20 patients thus far." (PMID 31438591, 2019). "A gene mutation of XYLT2, the isoform of XYLT1, results in spondylo-ocular syndrome (MIM: 605822), which is characterized by bone fragility, cataracts, and hearing defects." (PMID 36233030, 2022). "Families previously diagnosed with Spondylo-ocular Syndrome with autosomal recessive inheritance, moderately severe-to-severe osteoporosis, and eye and hearing involvement without variants in LRP5, were discovered through WES to have mutations in Xylotransferase-2 (XYLT2)." (PMID 38942908, 2024).
retinal detachment (3 papers, 2019 to 2025). An eye emergency condition which may lead to blindness if left untreated. "In particular, the presence of cataract, retinal detachment has been described thus far only in patients with XYLT2 mutations." (PMID 31438591, 2019).
linkeropathies (2 papers, 2019 to 2023). "To date, five genes, encoding various glycosyltransferases, have been linked to linkeropathies; besides the XYLT2 gene, there are the genes XYLT1 (OMIM * 608124), B4GALT7 (OMIM * 604327), B3GAT3 (OMIM * 606374), and B3GALT6 (MIM:* 615291)." (PMID 36833424, 2023). "Hearing loss is associated with mutations in XYLT2 while this is uncommon in the other linkeropathies." (PMID 31196143, 2019).
colon cancer (1 paper, 2023). "The most specific loci were in the exons of genes JAK1 and CHD3 (for endometrial cancer); BMPR2, ELAV3, GLYR1, and ZNF43 (for colon cancer); and XYLT2 (for stomach cancer)." (PMID 37894432, 2023).
Glucose intolerance (1 paper, 2025). Glucose intolerance (GI) can be defined as dysglycemia that comprises both prediabetes and diabetes. "XYLT2 deficiency disrupts GAG production in the extracellular matrix, resulting in impaired adipocyte differentiation, increased inflammation, and metabolic imbalances such as insulin resistance and glucose intolerance." (PMID 40963867, 2025).
Hypertension (1 paper, 2023). The presence of chronic increased pressure in the systemic arterial system. "Still, an increased expression of SVEP1, NRP1, RNASE1, QSOX1, and GKN1, along with decreased expression of XYLT2, CFH, LEP, and CETP serum levels were found in patients with hypertension." (PMID 37792298, 2023).
Kidney Cyst (1 paper, 2025). Abnormal fluid filled sac within the kidney, either acquired or congenital. "Although Xylt1 and Xylt2 are similarly expressed in adult mice, Xylt2 knockout mice develop postnatal liver and kidney cysts but no skeletal defects." (PMID 40806493, 2025).
lipodystrophy (1 paper, 2025). A congenital or acquired disorder characterized by abnormal loss or redistribution of the adipose tissue in the body. "Recent studies show that XylT2 is crucial for lipid homeostasis, as its deficiency leads to adipose tissue loss and lipodystrophy in mice." (PMID 40806493, 2025).
liver cancer (1 paper, 2025). An epithelial or non-epithelial malignant neoplasm that arises from the liver. "Although its role in cancer remains underexplored, recent studies suggest that elevated XYLT2 expression may correlate with poor prognosis in liver cancer." (PMID 40963867, 2025).
oesophageal cancer (1 paper, 2018). "MLL3 and FAT1 share connections across several cancer types, with both having several interaction in uterine cancer, while MLL2 exhibits many connections for stomach, and XYLT2 for oesophageal cancer." (PMID 30341300, 2018).
ovarian carcinoma (1 paper, 2025). A malignant neoplasm originating from the surface ovarian epithelium. "To determine whether GAG levels affect carboplatin activity, we generated GAG-deficient ES2 ovarian cancer cells using CRISPR-mediated knockout of xylosyltransferases XYLT1 and XYLT2, the enzymes responsible for the initial step in GAG biosynthesis." (PMID 41279644, 2025).
tumor (6 papers, 2010 to 2025). "Within the EGOT–miR-32-5p–XYLT2 axis identified in our ceRNA network, XYLT2 may contribute to hepatocarcinogenesis by modulating matrix composition and tumor–stromal interactions, warranting further mechanistic investigation." (PMID 40963867, 2025). "The expression levels of B3GAT3, XYLT1, XYLT2, B4GALT7, and B3GALT6 were significantly upregulated in OS tissues compared to those in non-tumor tissues, according to the analysis of the bulk RNA-seq dataset (PRJNA539828)." (PMID 38690160, 2024). "The full name of XYL2 is xylosyltransferase 2, and XYL2 participated in the proteoglycan (PG) biochemistry of multiple tumor tissues." (PMID 34987579, 2021). "Nonetheless, several genes significantly increase in tumors and impact patient survival (XYLT2, B3GAT3, EXT2) while HS3ST1 is decreased in tumor." (PMID 33585200, 2020).
cancer (3 papers, 2018 to 2025). A tumor composed of atypical neoplastic, often pleomorphic cells that invade other tissues. "However, the specific roles of SEC13, ALG1, FAM162A, GALK1, and XYLT2 in cancer remain unclear." (PMID 35963622, 2022).
XYLT2 also shares sentences with these, for which no sentence is quoted: Desbuquois dysplasia type 2 (2 papers); African trypanosomiasis (1); amblyopia (1); congenital heart disease (1); endometrial cancer (1); Insulin resistance (1); intestinal diseases (1); malaria (1); Nystagmus (1); osteoarthritis (1); osteoporosis (1); polycystic kidney disease (1); skeletal dysplasia (1); stomach cancer (1); Thrombocytopenia (1); uterine cancer (1); viral infection (1).